EGFR (epidermal growth factor receptor)
Diseases named in the same sentence as EGFR in open-access papers (continued):
Sharing a sentence is not in itself a finding about the gene and the disease.
tumor (continued). "Whereas cetuximab seems to affect the tumour cells directly, by abrogating EGFR activation, nimotuzumab would target both endothelial cells and tumour cells through a significant anti-angiogenic activity." (PMID 19293809, 2009). "In preclinical studies of tumour cell lines, radiation has been shown to activate growth factor signalling networks, for example, EGFR and IGFR leading to inhibition of radiation-induced cell death." (PMID 19672258, 2009). "Downstream of EGFR dimerization and activation are multiple processes that can result in cancer cell proliferation, prevention of apoptosis, tumor-induced angiogenesis, and activation of invasion and metastatic growth." (PMID 19636422, 2009). "Defining TGF-β1-initiated signaling events that cooperate with an activated EGFR to impact the protease-protease inhibitor balance in the tumor microenvironment is critical to the development of novel therapies for the clinical management of human cancers." (PMID 19365582, 2009). "Vandetanib greatly suppressed the tumour growth of the TKKK xenograft through anti-EGFR and VEGFR-2 inhibition, consistent with the in vitro study." (PMID 19319137, 2009). "High levels of EGFR protein expression strongly correlates with tumor metastasis and poor prognosis in EC." (PMID 19917135, 2009). "The rate of HNSCC tumours presenting immunohistochemical (IHC) protein overexpression was found to be 80%–90% for EGFR and 4%–39% for HER2." (PMID 19830244, 2009). "We found eight cases with a trend in favour of EGFR gene deregulation from primary tumour to metastasis and four cases with the opposite trend." (PMID 19293803, 2009). "We observed that this cluster of silent-tumours (n = 11), referred to hereafter using the 'silent' prefix, more frequently displayed high expression of EGFR (≥ 2+) gene products as compared with the rest of the cohort (Fisher's exact test, P = 0.0069)." (PMID 19589159, 2009). "Clinical studies have also shown that EGFR promotes resistance to radiation in many tumor types, including GBMs." (PMID 19828040, 2009). "In contrast, co-overexpression of dMyc with dEGFRλ produced a phenotype on par with that of repo>dEGFRλ;dp110CAAX, indicating that dMyc overexpression can substitute for PI3K activation and promote neoplasia when combined with EGFR signaling." (PMID 19214224, 2009). "It is possible that the mutations present in EGFR precipitate the altered oncogenic signal and make EGFR indispensable for tumor growth, which make the inhibitor or antibody function to inhibit tumor growth." (PMID 19178753, 2009). "Ample evidences support the critical role EGFR in tumor growth and progression, including angiogenesis, tumor cell proliferation and metastasis." (PMID 19917135, 2009). "RCC is characterized by the loss ofthe von hippel landau (VHL) gene, which leads to dysregulation of the VEGFR,PDGFR-β, transforming growth factor-alpha (TGF-) α, EGFR, and Raf pathways promotingangiogenesis, lymphangiogenesis, tumor cell growth, and survival." (PMID 19424511, 2009). "EGFR inhibition by cetuximab significantly reduced tumor repopulation during fractionated RT in a xenografted human model of SCC." (PMID 19284526, 2009). "Antigen-specific active immunotherapy is another potential therapeutic approach for the treatment of EGFR-positive tumor cells by breaking of immune tolerance against wild type or mutant-type EGFR." (PMID 19178753, 2009). "Decreasing activity of MAPK, which is a downstream molecule of the EGFR pathway, reduces tumour proliferation in vivo." (PMID 19319137, 2009). "This system stratifies results into six groups (disomy, low trisomy, high trisomy, low polysomy, high polysomy and gene amplification) according to the number of copies of the EGFR gene, chromosome 7 centromere and their frequency in tumor cells of the sample." (PMID 19889201, 2009). "After exhausting multiple therapeutic strategies, EGFR inhibition afforded him over 30 months of progression-free tumor control and significant palliation." (PMID 19527509, 2009).
tumor (continued). "MASI is frequently present in mutant EGFR and KRAS tumor cells, and is associated with increased mutant allele transcription and gene activity." (PMID 19826477, 2009). "Conversely, aberrant activity of the EGFR signaling cascade has been shown to play a key role in tumor cell growth and cell differentiation." (PMID 20028552, 2009). "Another trial evaluated EGFR mRNA expression and gene dosage, both assayed by quantitative PCR (qPCR) in tumor samples from patients with gefitinib-treated NSCLC." (PMID 19159467, 2009). "Taken into consideration a strong positive correlation between EGFR and vimentin expression, we have taken an effort to construct an immunopanel defining basal-type tumours as triple negative tumours that are vimentin-positive or basal cytokeratin-positive." (PMID 19695088, 2009). "As anti-EGFR monoclonal antibodies sensitise tumours, we investigated cetuximab's toxicity plus chemoradiation on CC cells, which express different EGFR levels." (PMID 19654571, 2009). "Tumour specimens of 178 NSCLC patients were collected and analysed for EGFR and KRAS mutation status by DNA sequencing, and for EGFR copy number by fluorescent in situ hybridisation." (PMID 19050706, 2009). "In conclusion, we identified miR-125a-5p, an EGFR-regulated miRNA, as a potential tumor metastasis suppressor." (PMID 19702827, 2009). "c-myc, another EGFR target gene that can obstruct the induction of apoptosis in tumor cells and lead to uncontrolled cell growth was reduced in the PDT plus Erbitux treated tumors." (PMID 19878607, 2009). "EGFR activation induces the cell cycle progression, inhibition of apoptosis and angiogenesis, promotion of invasion/metastasis, and other tumor promoting activities." (PMID 19747398, 2009). "Over-expression of EGFR played an important role in tumor initiation and progression of RCC, so up-regulation of EGFR was correlated with high-grade tumors and a worse prognosis." (PMID 19747398, 2009). "It has been well established that the core of solid tumors is hypoxic, and that hypoxic tumor environment is sufficient to trigger EGFR expression in tumors." (PMID 19878607, 2009). "Efficacywas evaluated in patients with 1% or greater EGFR tumor staining by IHC anddisease progression while on or within 6 months of the most recentchemotherapy." (PMID 19424511, 2009). "Epidermal growth factor/EGFR autocrine and paracrine processes driving tumour cell proliferation has formed the basis for chemotherapeutic drug targeting of EGFR in some cancers." (PMID 19088723, 2009). "Activation of EGFR promotes processes responsible for tumour growth and progression, including proliferation and maturation, angiogenesis, invasion, metastasis, and inhibition of apoptosis, making it a popular target for anti-cancer therapy." (PMID 19755995, 2009). "The animals with tumors were assessed after acute or chronic treatment with goserelin, and in all the animals VEGF and EGFR expression was examined both in plasma and tumor homogenates by enzyme immunoassay." (PMID 19491505, 2009). "Radiosensitisation of tumour cell mediated by EGFR antagonists is supported by preclinical and clinical studies, also suggesting the possibility of successful radiosensitisation in this setting." (PMID 19293809, 2009). "The authors further showed that 23 of 34 patients with EGFR-positive tumours had a disease recurrence (67.0%), compared with 2 of 24 patients (8.3%) who had EGFR-negative PCa." (PMID 19888222, 2009). "Despite the fact that greater than 75% of MM tumour samples overexpressed EGFR, clinical trials targeting EGFR in MM with tyrosine kinase inhibitors have yielded some objective responses, but not with the desired frequency." (PMID 19755995, 2009). "The EGFR is expressed in many normal human tissues and has been found to be overexpressed in a large variety of tumours." (PMID 19773760, 2009).
tumor (continued). "In a preclinical model of gastric cancer, inhibition of VEGF and EGFR signaling resulted in significantly improved inhibition of tumor growth." (PMID 20016807, 2009). "Cetuximab, a humanized mouse anti-EGFR IgG1 monoclonal antibody, improved locoregional control and overall survival in combination with radiotherapy in locally advanced tumours but at the cost of some increased cardiac morbidity and mortality." (PMID 19828033, 2009). "Many of the genes identified during promotion (e.g. Ereg, Hbegf, and Spp1) can signal through EGFR or are involved in EGFR signaling events which can then lead to cell growth and eventual tumor development." (PMID 19925653, 2009). "Vandetanib is a tyrosine kinase inhibitor of both VEGFR-2 and EGFR, and preclinical studies have confirmed its anti-tumour effects in a range of cancer types." (PMID 19319137, 2009). "All tumors in the EGFR proteomic tumor class had deletion of the Ink4a/ARF locus compared with only 3/17 (18%) in the other groups." (PMID 19915670, 2009). "In certain epithelialmalignancies, moreover, resistance to TGF-β1-mediated growth suppression is often coupled withEGFR amplification or dysregulated EGFR signaling, particularly during thelater stages of tumor development." (PMID 19365582, 2009). "The most significant finding of this study was that the GEPR was capable of predicting progression-free survival in another tumor type than that on which the model was built, and with another EGFR-targeted agent." (PMID 19439077, 2009). "EGFR is a member of the HER (ErbB) family of human epidermal growth factor receptors that can promote tumor cell proliferation in a variety of epithelial malignancies." (PMID 19386128, 2009). "Total EGFR was the antigen with the highest expression levels and it was detected in all tumor samples." (PMID 19765296, 2009). "A predicted consequence of increased blood flow to a tumor would be enhanced drug delivery, which would have obvious clinical implications for the combination of anti-EGFR therapy and chemotherapy." (PMID 19657384, 2009). "This information further serves as preclinical background for clinical investigations involving anti-EGFR antibodies with radiation in human GBM, a tumour relatively resistant to the treatment with other well known anti-EGFR agents, such as Iressa and Tarceva." (PMID 19293809, 2009). "Eleven patients having tumour EGFR expression by immunohistochemistry with low serum EGF and TGF-α levels showed a 100% RR compared to 37.0% in the remaining 27 patients (P<0.001)." (PMID 19127259, 2009). "Over-expression of EGFR is thought to play an important role in tumor initiation and progression of RCC, since up-regulation of EGFR has been associated with high grade and a worse prognosis." (PMID 19747398, 2009). "For EGFR, 39 of the 240 tumours (16%) were IHC positive, whereas 59 tumours (24.5%) were kRT–PCR positive." (PMID 18985033, 2008). "On the basis of our previous in vitro studies in MDA-MB-231 cells, we postulated that the inhibition of both EGFR and mTOR expressions would be important mechanisms for tumour suppression after combination treatment." (PMID 18797454, 2008). "In order to confirm our findings, we repeated the immunohistochemistry from serial sections in all tumour specimens that exhibited EGFR-negative and p-EGFR-positive staining and the obtained results were identical." (PMID 19238633, 2008). "In this study, using immunohistochemical methods, we investigated the relationship between Id-1 and such well-known prognostic factors as tumour grade and tumour stage and such molecules as EGFR and VEGF." (PMID 19014499, 2008). "The epidermal growth factor (EGF) and EGF receptor (EGFR) families play important roles in the hyperplastic growth of several tissues as well as tumor growth." (PMID 18439312, 2008). "There was a significant relation between the tumour grade and the degree of staining for Id-1, EGFR and VEGF." (PMID 19014499, 2008).
tumor (continued). "It is similarly unlikely that the lower mean number of tumour cells available for EGFR FISH analysis in cytological specimens selected for ‘high polysomy’." (PMID 18087280, 2008). "Oncogenic loci cyclin D1 (CCND1), HER2, and EGFR were amplified in 3.5–6.7% of tumours and frequently contained amplicons <1 Mb." (PMID 18349818, 2008). "Initial retrospective studies showed an average response rate to EGFR-TKI of 75% for NSCLC with EGFR mutations that contrasted with a low response rate of <10% for tumours with wild-type EGFR gene." (PMID 18087280, 2008). "In human solid tumors, over-activation and/or dysregulation of EGFR promotes processes involved in tumor progression, including invasion, angiogenesis, metastasis, and resistance to anticancer treatment with blocking apoptosis." (PMID 18519000, 2008). "Epidermal Growth Factor Receptor (EGFR) is a key target molecule in current treatment of several neoplastic diseases." (PMID 18380891, 2008). "EGFR and KRAS mutations are predominantly mutually exclusive with very rare tumours containing both genes mutated." (PMID 18495026, 2008). "It is also known that several EGFR inhibitors, such as monoclonal antibodies, result in a concurrent downregulation of tumour-induced, VEGF-mediated angiogenesis." (PMID 18522728, 2008). "Tumours were obtained from patients of US (n=143) and Korean (n=167) origin and screened for LKB1, KRAS, BRAF, and EGFR mutations using RT—PCR-based SURVEYOR-WAVE method followed by Sanger sequencing." (PMID 18594528, 2008). "In non-small-cell lung cancer (NSCLC), epidermal growth factor receptor (EGFR) and K-RAS mutations of the primary tumour are associated with responsiveness and resistance to tyrosine kinase inhibitors (TKIs), respectively." (PMID 19238633, 2008). "In our experimental model it is difficult to correlate the global gene expression profile and tumor sensitivity or resistance to treatment with the EGFR inhibitors." (PMID 18691415, 2008). "Several preclinical studies have examined the anti-tumour activity of inhibitors of EGFR and anti-angiogenic agents in combination and have demonstrated at least additive, if not synergistic, effects." (PMID 18577994, 2008). "Recent studies seeking new treatment alternatives for advanced stage tumours have shown that EGFR and VEGF are new targets." (PMID 19014499, 2008). "This study demonstrated the existence of a significant discordance of EGFR and K-RAS mutations occurring in primary tumours and their corresponding metastases in patients with NSCLC." (PMID 19238633, 2008). "EGFR expression by tumour cells was detected byimmunohistochemistry in 36 out of the 42 (86%) valuable patients with MPNST;percentages were higher in the NF1 subgroup (95% versus 75%; P = .06; Chisquare test)." (PMID 18769552, 2008). "These concentrations are well above the pharmacologically relevant concentrations, reflecting a partial dependency of tumour cell lines to EGFR signalling." (PMID 18506149, 2008). "The primary objective of this phase I study was to determine the MTD, recommended dose (RD), safety, tolerability, pharmacokinetic and pharmacodynamic profile of matuzumab combined with ECX in advanced OG tumours expressing EGFR." (PMID 19238629, 2008). "Tumour cells showed positive staining for Id-1 in 43 cases (93.5%), for EGFR in 41 cases (89%) and for VEGF in 42 cases (91%)." (PMID 19014499, 2008). "In analysis of the entire tumor cohort, high levels of Jab1, EGFR, and S100A7 were seen in 154/424 (36%), 42/424 (10%), 144/424 (34%) cases, respectively." (PMID 18534028, 2008). "In order to investigate the relation between tumour stages and staining with Id-1, EGFR and VEGF antibodies, the tumours were divided into two groups based on Dukes' classifications: Group 1 (Dukes' stage A+B, n = 19) and Group 2 (Dukes stage C+D, n = 27)." (PMID 19014499, 2008).
tumor (continued). "Using the 75th percentile, patients whose tumours had increased EGFR mRNA expression had significantly reduced OS (22 out of 67 deaths in EGFR-positive vs 38 out of 200 deaths in EGFR-negative patients, log-rank P=0.022) (Figure 2A1)." (PMID 18985033, 2008). "Tyrosine kinase activity of epidermal growth factor (EGFR) promotes tumor cell proliferation, cell survival, angiogenesis, invasion, and metastasis, and its specific inhibition by gefitinib, a synthetic anilinoquinazoline, has been demonstrated." (PMID 21892326, 2008). "Here, it becomes clear that a better understanding of the mechanism of action of EGFR therapeutics, and studies on how tumor cell resistance can be circumvented will further contribute to optimize treatment regimes." (PMID 18702090, 2008). "The epidermal growth factor receptor (EGFR) is a member of the ErbB/HER family of receptor tyrosine kinases (TK), frequently overexpressed in human tumours and directly implicated in the control of cell growth, apoptosis and angiogenesis." (PMID 18665191, 2008). "We analyzed tumor tissues from 32 EGFR-positive mCRC patients receiving cetuximab/irinotecan combination and evaluable for treatment response." (PMID 18544172, 2008). "The effects of EGFR activation on tumour cells are multiple and convergent, thus favouring uncontrolled cell growth with an increase in cell mobility and cell proliferation, a decrease in apoptotic machinery and stimulation of angiogenesis." (PMID 18506149, 2008). "In summary, we have demonstrated that the combination of EGCG+tamoxifen significantly reduced ER-negative tumour growth and that this was driven primarily by an enhanced effect by the decreased protein expression of the EGFR, mTOR, and CYP1B1." (PMID 18797454, 2008). "EGFR and pEGFR coexpression appears to be more representative of EGFR dynamics in tumour than solely EGFR or pEGFR expression." (PMID 18522728, 2008). "NCX-4040, in combination with cisplatin, inhibited tumor growth by downregulation of EGFR and STAT3 signaling." (PMID 18302761, 2008). "Probably, in EGFR-positive/pEGFR-positive tumours, the total number of receptors is greater; thus, there are more receptors available for subsequent phosphorylation." (PMID 18522728, 2008). "One main biological objective of this study was the serum extra-cellular binding domain of EGFR as a surrogate marker of tyrosine-kinase inhibition and as a predictor of tumour response." (PMID 22275961, 2008). "The total number of tumours with data available from both IHC and kRT–PCR was 240 and 228 for EGFR and HER2, respectively." (PMID 18985033, 2008). "Preclinical studies have shown that the anti-EGFR mAb cetuximab markedly increases the cytotoxic effect of chemotherapy or radiation therapy in various EGFR-expressing tumour cell lines." (PMID 18253126, 2008). "Phospho-EGFR was observed in circulating tumor cells of two (33%) early and six (86%) metastatic EGFR-positive patients." (PMID 18822183, 2008). "Epidermal growth factor receptor and K-RAS mutation status was different between primary tumours and corresponding metastases in 7 (28%) and 6 (24%) of the 25 patients, respectively." (PMID 19238633, 2008). "In this study, the expression of pY1173-EGFR was different between primary tumours and corresponding metastases in eight (50%) patients, whereas EGFR expression was discordant in two (10%) patients." (PMID 19238633, 2008). "Of thirty-one invasive cancers, sections containing adequate amounts and quality of tumour were available to be examined for the expression of EGFR and HER2-neu and gene copy number by immunohistochemistry and FISH." (PMID 18182111, 2008). "As we have previously shown that EGCG+4-OHT produces an earlier and greater apoptotic response and elicits a greater inhibition of pEGFR in MDA-MB-231 cells, the role of the EGFR and other downstream cell signalling proteins were determined in tumour extracts." (PMID 18797454, 2008).